HIF1A (hypoxia inducible factor 1 subunit alpha)
Diseases named in the same sentence as HIF1A in open-access papers (continued):
Sharing a sentence is not in itself a finding about the gene and the disease.
tumor (continued). "In contrast, stress-mediated TAp73 activation would likely lead to suppression of the HIF1-α circuitry, thereby shutting down angiogenesis to enhance tumor suppression." (PMID 26711266, 2015). "The expression of BNIP3, a Bcl-2 family member, correlates with HIF-1α expression levels in various types of tumor cells." (PMID 26711814, 2015). "A highly significant reduction of the number of HIF-1α-positive cells in tumor sections was observed from 5 to 7 days of treatment (P < 0.0001) but returned to the control value at 9 days suggesting a transient effect of the anti-S1P mAb." (PMID 25915662, 2015). "Tumor incidence was slightly decreased for HIF1α(PP) cells (3/5 vs 4/5 for the other two cell types)." (PMID 25893706, 2015). "Previous reports suggested that the interaction between HIF-1α and Notch1 can influence tumor angiogenesis." (PMID 25723392, 2015). "Von Hippel Lindau tumor suppressor, which functions as an E3 ubiquitin ligase, interacts with the hydroxylated proline residues of HIF-1α and brings about assembly of a complex that activates an ubiquitin-dependent proteasome." (PMID 26098428, 2015). "In rapidly growing tumor, hypoxic conditions strongly activate the expression of the transcription factor HIF-1α, which in turn stimulates the expression of VEGF proteins in tumor cells." (PMID 26378810, 2015). "In these reports, DEC2 was found to physically interact with and promote HIF-1α degradation, contributing to its suppressive effects on tumor progression and metastasis." (PMID 25884381, 2015). "Increased HIF-1α expression triggers the activation of a large array of genes involved in tumor growth, glycolytic switch, angiogenesis, and epithelial-mesenchymal transition (EMT)." (PMID 25821081, 2015). "The resultant upregulation of hypoxia inducible factors (HIF1α and HIF2α, also known as HIF1A and EPAS1) due to failure of ubiquitination by the mutated VHL leads to vast neovasculature, which subsequently promotes tumour growth." (PMID 25853938, 2015). "It is now known that tumour cells express large amounts of either or both MCT1 and MCT4, with the most aggressive tumours often expressing mainly MCT4 which is up-regulated by over-expression of hypoxia-inducible factor 1α (HIF-1α)." (PMID 25437897, 2015). "Hypoxia-inducible factor-1α (HIF-1α) is a principal molecular mediator for tumor angiogenesis, and Notch pathway dysregulation is a leading genetic instability in HNSCC." (PMID 25723392, 2015). "In cancers, HIF-1α changes expression of genes leading to increased tumor metabolism and metastasis, creating a very aggressive tumor." (PMID 26010887, 2015). "Adaptation of tumor cells to growth under hypoxic conditions has been primarily attributed to the accumulation of the hypoxia-inducible transcription factors HIF-1α (expressed by the HIF1A gene) and HIF-2α (expressed by the EPAS1 gene)." (PMID 26057707, 2015). "Results showed that EGFR inhibitors at clinically relevant doses can reduce the regulation of HIF-1α and Notch1 in this tumor type with limited side effects." (PMID 25723392, 2015). "Probably this also explains why a lack of correlation between hypoxia measurements and expression of HIF-1α and its target genes have been seen not only in some of the tumours in the present study, but also in other studies." (PMID 26501874, 2015). "Study showed that the level of HIF-1α protein is essential for tumor cells to adapt to and survive from hypoxic microenvironment." (PMID 25816356, 2015). "In an in vivo mouse model transdermal NTG patches attenuated tumour growth via a mechanism dependent on adaptive immune effector cells, presumed to be due to inhibition of HIF-1α accumulation and hypoxia induced PD-L1 expression." (PMID 26435741, 2015). "In vivo, SQE supplementation suppressed tumor growth in a xenograft model by down-regulating stem cell markers and β-catenin as well as HIF-1α signaling." (PMID 25941936, 2015).
tumor (continued). "We then examined the correlation between OPN and HIF-1α expression by IHC in tumor tissue samples from patients with HCC." (PMID 25749383, 2015). "Examinations at high magnification revealed that pimonidazole and HIF-1α were localized primarily in the keratinizing centers of tumor cell nests, whereas CAIX showed an almost diametrical staining pattern with expression only in the periphery of these nests." (PMID 26502718, 2015). "This mitochrondrial tumor suppressor was later found to decrease hypoxia-inducible factor 1α (Hif1α) and genomic instability, which led to cellular metabolic reprogramming and eventually limited carcinogenesis." (PMID 26317998, 2015). "The expression of HIF-1α was found to be significantly higher in HCC patients with increased tumor size (P < 0.001), vascular invasion (P = 0.025), intrahepatic (P = 0.002) and distant metastasis (P < 0.001)." (PMID 26078356, 2015). "Inhibiting HIF-1α expression by increasing the expression of certain anti-tumor factors acts as a therapeutic tool for the molecular treatment of tumors." (PMID 25695729, 2015). "LOX has been identified as an important regulator of the hypoxia-induced tumor progression pathway through a HIF-1α-dependent mechanism in numerous cancer types, such as breast, head and neck, prostate and renal cell carcinomas." (PMID 25790191, 2015). "To determine if OPN maintains tumor stemness and self-renewal characteristics by activating HIF-1α gene expression, we overexpressed HIF-1α in OPN-depleted HCCLM3 cells." (PMID 25749383, 2015). "The HIF-1α mRNA level significantly increased with the size of the primary tumor (pT3-4) (p < 0.001), the presence of nodal metastases (pN1-3) (p < 0.001), and tumor grade (p = 0.004)." (PMID 25412955, 2015). "Immunohistochemical staining of formalin-fixed, paraffin-embedded tumor tissues demonstrated the presence of HIF1α and CAIX, which showed typical, hypoxia-related expression patterns." (PMID 25997619, 2015). "Hypoxia inducible factor-1α (HIF-1α) stimulates cytokines expression, increases tumor dissemination, cell proliferation, angiogenesis and survival." (PMID 26078356, 2015). "We found well-segregated tumor—clusters representing high and low HIF-1α/PGK1-expressors which accounted for differential expression of Notch signaling genes." (PMID 25734817, 2015). "The presence of hypoxia, measured by tumour expression of HIF-1α or surrogate markers of hypoxia such as glucose transporter (GLUT)-1 or carbonic anhydrase 9 (CA9), has been shown to be associated with poorer survival in ovarian cancer patients." (PMID 26205780, 2015). "Commonly used measurement for tumor hypoxia includes HIF-1α immunohistochemistry assessment, oxygen electrode probe, PET radiotracers such as 18F-FMISO, 18F-FAZA, Cu (II)-ATSM." (PMID 25786221, 2015). "Although we and others previously found hypoxic conditions in the core of larger tumor spheroids, HIF-1α remained largely unaffected in the relatively small MC-38 3D spheroid cultures." (PMID 25978030, 2015). "SEPT9_i1 overexpression is known to control the HIF-1α pathway and to stabilize the c-Jun N-terminal kinase, leading to enhanced proliferation and tumor growth." (PMID 26460824, 2015). "HIF1α induced by hypoxia turns on a transcription program that promotes an aggressive tumor phenotype and resistance to therapies via triggering of critical genes." (PMID 25714028, 2015). "Induction of HIF-1α by hypoxia—a characteristic feature of the tumor environment—promotes the transcription of target genes that lead to invasiveness, metabolic shift, angiogenesis, and metastatic potential." (PMID 26474388, 2015). "MCF-7/HIF-1α cells exhibited quicker and larger xenograft tumor formation than those of formed by MCF-7/vector cells." (PMID 25929338, 2015).
tumor (continued). "On the basis of these findings, a number of studies investigated the stimulatory action of copper on VEGF production and tumor angiogenesis and the repressive effects exerted by copper-chelating on HIF-1α mediated expression of VEGF." (PMID 26415222, 2015). "Due to their role in tumor progression, HIF-1α and HIF are targets for the development of new small molecular inhibitors." (PMID 26547841, 2015). "In tumor cells, the antiapoptotic and proangiogenic effects of nicotine have been attributed to its ability to stimulate HIF-1α through nAChRs." (PMID 26361040, 2015). "Recalling previous studies on the capability of copper chelating agents to elicit anti-tumor effects, we have also evidenced that these chemicals exert an inhibitory action on HIF-1α/GPER/VEGF transduction pathway." (PMID 26415222, 2015). "Both Stat3 and HIF-1α have been revealed to drive tumor angiogenesis, metastasis and drug resistance." (PMID 26202747, 2015). "Levels of HIF-1α protein in tumors decreased as dietary ascorbate supplementation increased for both tumor models (P < 0.001)." (PMID 25354695, 2015). "In vitro and in vivo our study revealed that pantoprazole (PPZ) inhibited tumor cells proliferation, induced apoptosis and decreased the expression of HIF-1α protein." (PMID 29147412, 2015). "A significant reduction in tumor burden and in the expression levels of both HIF-1α and EWS-FLI-1 proteins were observed in mice after treatment." (PMID 26393682, 2015). "This tumour microenvironment produces various factors, such as TNFα, TGFβ, Wnt, and HIF-1α, all of which stimulate a transient epithelial-mesenchymal transition (EMT) to promote cancer progression, invasion, and metastasis." (PMID 26508818, 2015). "In this scenario, miR-182 would promote the irreversible activation of the HIF1α pathway and thereby the stable switching of the cellular state for tumor growth and angiogenesis under the hypoxic condition." (PMID 26205124, 2015). "Tanshinone-1 was revealed to lower the 6-h-hypoxia-induced accumulation of HIF-1α protein in a concentration-dependent manner in different tumor cells including MCF-7, SKOV3, HCC1937, A549 and HeLa cells." (PMID 26202747, 2015). "HIF-1α was observed in the cell nuclei and cytoplasm of the tumor cells, whereas CA-IX, GLUT-1 and VEGF were predominantly localized in the cell membrane and cytoplasm." (PMID 26622782, 2015). "Initially, our data showed that high expression levels of HIF-1α in clinical tumor specimens were correlated with advanced tumor stage and poor differentiation, suggesting that HIF-1α is a potential biomarker for NB progression." (PMID 25811359, 2015). "Another EMH is osteopontin (OPN), which is expressed independently of HIF-1a and is involved in the adhesive cell–matrix interaction and is considered a protein involved in tumor development and progression 15,16." (PMID 25919147, 2015). "After binding to its cognate enhancer sequence in the promoters of its target genes, HIF-1α regulates the transcription of multiple genes in tumor cells and their surrounding stromal cells." (PMID 25843954, 2015). "In order to disrupt new blood vessel formation in tumor, it is a key to inhibit the expression of the VEGF and HIF-1α proteins in tumor cells." (PMID 26378810, 2015). "In response to hypoxia, HIF-1α and a broad array of its downstream targets are synthesized de novo as a consequence of defects displayed by a variety of tumor suppressors in concert with organ-specific cancer cell invasion and migration." (PMID 26528854, 2015). "Since overexpression of HIF-2α in 786-O cells has the opposite effect on tumor xenograft growth to re-expression of wild-type HIF-1α, we next examined the effect of increasing HIF-2α levels on HIF binding and gene expression." (PMID 26262842, 2015).
tumor (continued). "Here we demonstrate, for the first time, that inhibition of HIF-1α expression by PX-478 enhances immunogenicity of Gem and elicits tumor-specific DC phagocytic and cytotoxic T cell responses to PDAC cells." (PMID 25544770, 2015). "Western blot analysis revealed that the expression of PI3K, phosphorylated Akt (S-473) and HIF-1α was significantly lower in the EAC tumor tissue of the 2-DG fed mice than in the tumors of control mice." (PMID 26135741, 2015). "Under hypoxic conditions within the tumor mass, hypoxia-inducible factor-1a (HIF-1a) becomes up-regulated, which in turn induces high expression of CXCR4 on tumor cells." (PMID 26091099, 2015). "During tumor progression, the tumor mass develops hypoxic zones where HIF-1α can induce the accumulation of VEGF proteins." (PMID 25789317, 2015). "Thirdly, targeting of HIF-1α and hypoxic-related factors should impair cancer cell survival either by attenuating tumor glucose metabolic processes or by inhibiting VEGF induced prosurvival and angiogenesis pathways." (PMID 25685782, 2015). "Accordingly, we demonstrated a strong positive association between Nampt/PBEF/visfatin and HIF1α expression, both in tumor and normal tissue, with HIF1α being one of independent predictors of its expression in CRC." (PMID 26075243, 2015). "Colony formation results showed that the decreased tumor cells growth rate following HIF-1α knockdown can be rescued by the up-regulation of SCF (p<0.05)." (PMID 25799412, 2015). "HIF-1α is a major factor involved in tumor progression including angiogenesis and metastasis by regulating mitogen activated protein kinases under hypoxic conditions." (PMID 25742790, 2015). "We demonstrated that THC, one of the active anticancer forms of CUR in vivo, markedly inhibited tumor angiogenesis in CaSki-implanted female nude mice models by downregulation of HIF-1-α, VEGF/VEGFR-2 pathway." (PMID 25789317, 2015). "The transcription factor hypoxia-inducible factor-1α (HIF-1α) is accumulated in tumor cells under hypoxic conditions and is involved in the acquired resistance towards cancer therapy and adaptation to hypoxia." (PMID 26017562, 2015). "Collectively, all these results suggest that OA inhibits tumor growth through the regulation of SIRT3-mediated HIF1α destabilization." (PMID 25855962, 2015). "HIF-1α is able to interact with specific signaling pathways that have important roles in adapting to hypoxia in tumor cells." (PMID 25997455, 2015). "This anti-tumor effect was associated with downregulation of HIF-1α, PDK1 and c-Myc, and a reduction in the number of tumor vessels." (PMID 26398947, 2015). "HIF1α in tumor cells is induced and activated under hypoxia condition, while AP-1 functions under both normoxia and hypoxia conditions." (PMID 26287601, 2015). "The miR-182-HIF1α positive feedback loop results in hyperactivation of HIF1α signaling and increased angiogenesis in tumor growth, thereby helping the cancer cells survive under hypoxic environment." (PMID 26205124, 2015). "A recent study showed that STAT3 and HIF-1α form transcription factor complexes that drive target gene expression, providing a direct cooperative link between STAT3 and HIF-1α in tumor progression." (PMID 26343197, 2015). "As an important transcription factor, HIF-1α has important functions in cancerous transformation, chemoradiotherapy resistance, and tumor progression." (PMID 25799412, 2015). "Hypoxia inducible factor 1 (HIF1A) functions in angiogenesis, ready to feed any new tumor that begins to form." (PMID 25751518, 2015). "To further demonstrate the regulatory effect of HIF-1α we found in vitro, we established a tumor xenograft model." (PMID 25811359, 2015). "Yet, a decrease in tumor sphere formation and anchorage-independent growth was observed in HIF1α(PP)-induced U-118 MG cells." (PMID 25893706, 2015).
tumor (continued). "Many studies have revealed that HIF-1α plays important roles in tumor development, inflammatory metabolic diseases and fibrosis." (PMID 26098428, 2015). "HIF-1α overexpression in tumor cells correlates with worse clinical outcomes following radiation therapy." (PMID 25887043, 2015). "Taken together, these findings are consistent with the observation of significantly higher Hypoxia-inducible factor 1-α (HIF-1α) levels in tumor tissues (P = 0.0002), indicating that HIF-1α drives the up-regulation of these metabolic enzymes." (PMID 25945836, 2015). "Different pathways are responsible for inducing EMT and metastasis of tumor cells; among them, NO is a common denominator of HIF1α and endoplasmic reticulum (ER) stress." (PMID 25849745, 2015). "The anti-cancer effect of cisplatin was shown to be linked to oxidative stress of tumor cells and an increased level of HIF-1α has been shown to contribute to cisplatin resistance in tumor cells." (PMID 25797253, 2015). "This special tumor microenvironment enhances HIF-1α over-expression in the majority of human cancers and their metastases, where HIF-1α induces gene expression to promote survival." (PMID 26402672, 2015). "HIF-1α acts as a target factor for cancer therapeutics, as its function is regulated by growth factors and genetic abnormalities involved in tumor progression." (PMID 25695729, 2015). "Stromal CTGF expression did not correlate with other clinicopathologic features such as age, tumor type, tumor size, lymph node status or hormonal status, or HIF-1α expression." (PMID 25738829, 2015). "ITZ, alone and in combination with cisplatin, inhibited growth of primary NSCLC xenografts, increased expression of HIF1α, and reduced tumour vascular area compared to vehicle-treated controls." (PMID 25932045, 2015). "Anti-HIF-1α-labeled sections showed a marked decrease in staining of tumor cells in mice treated for 5 days with the anti-S1P mAb." (PMID 25915662, 2015). "In particular, targeting HIF-1α by antisense plasmid in xenografted mice led to NK cell-dependent tumor rejection." (PMID 26441986, 2015). "HIF-1α accumulates in cells under hypoxia induced by the rapid growth and increase in tumor oxygen consumption, enabling the cells to adjust to the state of hypoxia through gene expression." (PMID 26017562, 2015). "As demonstrated in our previous investigations, in hypoxic tumor microenvironment HIF-1α mediates the expression of GPER that contributes to the regulation and function of VEGF." (PMID 26415222, 2015). "Hypoxia can arrest tumor cells proliferation, however, another study showed that the increased hypoxic stress can accelerate the growth of HIF-1α tumors." (PMID 25816356, 2015). "HIF-1α is induced under hypoxia and plays an important role in tumor progression by upregulating genes that control angiogenesis, metastasis, and resistance to oxidative stress." (PMID 25887043, 2015). "Collectively, our findings suggest that PZH can inhibit hypoxia-induced tumor angiogenesis via suppression of HIF-1α/VEGF-A pathway." (PMID 25649293, 2015). "Consistent with the observation using Millipore filters, tumour slices cultivated statically using both types of Alvetex support accumulated HIF1α at the media interface." (PMID 26647838, 2015). "OS curves estimated by Kaplan-Meier showed that tumor patients with low FOXO3a or high HIF-1α expression had significantly poorer prognosis compared with patients with high FOXO3a or low HIF-1α levels (P < 0.001, and P = 0.012, respectively)." (PMID 29147412, 2015). "In contrast, chemo-residual tumor cells emanating from our short-term chemotherapy treatment model exhibited reduced HIF-1α mRNA and protein levels." (PMID 26141457, 2015). "Early studies performed with RAS-transformed MEFs derived from Hif1a-/- mice showed that oncogenic HRAS is able to induce full tumor vascularization in the xenotransplants." (PMID 26000250, 2015).